TNF (tumor necrosis factor)
Diseases named in the same sentence as TNF in open-access papers (continued):
Sharing a sentence is not in itself a finding about the gene and the disease.
cancer (continued). "This led to a reduction in cancer cell proliferation, which, in part, can be attributed to its ability to down-regulate the production of pro-inflammatory cytokines like TNF in CML patients." (PMID 38337668, 2024). "In diverse cancer lineages (colon and lung cancer, melanoma, and leukemia), the synergistic action of TNF-α and IFN-γ can trigger the activation of a variety of signaling switches such as GSDMD, GSDME, caspase-8, and MLKL." (PMID 38553639, 2024). "We also Meanwhile, this study proved that the downregulation of LINC01929 significantly inhibited cancer cell growth and induced cell cycle arrest potentially through modulation of the TNF signalling pathway and its downstream STAT3." (PMID 39586790, 2024). "RSV induces polarization and immune response of CD8+T lymphocytes and the production of cancer preventing IFNγ and TNFα cytokines." (PMID 39220125, 2024). "TNFα increased cancer cell sensitivity to the chemotherapeutic drugs oxaliplatin (OXP) and 5-flurouracil (5-Fu)." (PMID 38195677, 2024). "TNF activates the NF-κB transcription factor, which is a crucial mediator in inflammation-induced cancer." (PMID 38276239, 2024). "The FDA has issued several cancer warnings and a cancer surveillance requirement for patients aged <30 treated with tumor necrosis factor (TNF) inhibitors (TNF-I), although the initial FDA report was criticized for methodological reasons." (PMID 38610975, 2024). "Several lines of evidence show that TNF-α is involved in the transformation of inflammation into cancer; moreover, its overexpression is reported in the CRC tissues and correlates with the CRC stages." (PMID 38082190, 2024). "A recent systematic review shows that cancer patients engaged in various exercise regimens exhibited improvements in immunity, including reductions in TNF-α, CRP, IL-8, and IL-6, along with an increase in NK cells." (PMID 39064705, 2024). "Intercalarily, with these biotic applications, a decline in the values of IL-1, IFN-γ, TNF-α, and neopterin and a rise in the values of IL-10/-12/-13 were observed in cancer cells." (PMID 39045970, 2024). "PC inhibits the development of E coli by modulating the inflammatory response, the cancer pathway, the TNF signaling pathway and the PI3K-Akt signaling pathway." (PMID 38875382, 2024). "KEGG pathway enrichment showed that “cytokine−cytokine receptor interaction”, ′′pathways in cancer, and “TNF signaling pathway” were the most highly enriched pathways." (PMID 39422063, 2024). "Here, we investigated the impact of FYD on the heterogeneous adherence between TNF-α-induced cancer cell CNE1 and HUVECs." (PMID 38738179, 2024). "Increased production of IL-1, IL-6, and TNF-α was observed in phytohemagglutinin-stimulated cultured peripheral blood mononuclear cells isolated from advanced cancer patients." (PMID 39114348, 2024). "These herbs exhibit effectiveness against inflammatory cytokines, such as IL-6, IL-8, and TNF-alpha; inhibit cancer growth; regulate VEGF expression; and modulate the immune system." (PMID 38543097, 2024). "Monocytes secrete a variety of pro-inflammatory cytokines, such as interleukins IL-1, IL-6, IL-10, and TNF-α, which have been correlated with reduced survival and a worse prognosis in patients with malignant tumors." (PMID 39493767, 2024). "Laboratory murine cancer models suggest that TNFα promotes malignancy by influencing both initiated cancer-developing cells and inflammatory cells in the microenvironment." (PMID 38051374, 2024). "Here, we found that the addition of TNFα increased the immunogenicity of OXP-treated cancer cells via the PANX1-ATP-P2RX7 axis." (PMID 38195677, 2024).
cancer (continued). "Tumor necrosis factor (TNF), an inflammatory cytokine involved in various autoimmune and inflammatory diseases and cancer, has been shown to enhance PDAC growth." (PMID 39178856, 2024). "We first measured the expression of genes involved in adipocyte differentiation (PPAR-γ, AP2, HSL, Adiponectin, Leptin), cancer-associated fibroblast (CAF) markers (LIF, FAP, α-SMA), and inflammation (IL-6, IL-8, IL-1β, CXCL-10, TNF-α)." (PMID 39072314, 2024). "Interleukin-6 (IL-6) has also been identified as a potential factor that interacts with TNF-α or acts independently to induce systemic inflammation in the context of cancer cachexia." (PMID 38334644, 2024). "It aimed to disrupt the paracrine inflammatory loop, where chemotherapy-induced cytotoxic stress leads to TNF-α secretion by endothelial cells, promoting cancer-cell production of CXCL1/2 and recruitment of MDSCs." (PMID 39206193, 2024). "Docetaxel induces the production of interferon-α and tumor necrosis factor-α (TNF-α) which downregulate cell death in paclitaxel-resistant cancer cells." (PMID 39003454, 2024). "In the context of targeting immune cells in cancer treatment, PANoptosis is activated to induce inflammatory cell death, mediated by the synergism of cytokines, such as TNF-α and IFN-γ, which are produced by immune cells." (PMID 38169587, 2024). "Overall, TNF-α-targeted strategies hold potential for improving cancer pain management in the future personalized medicine approach." (PMID 38940936, 2024). "Owing to its dual function in TNF, cIAP’s regulatory role of cIAP in cancer and the immune system is critical." (PMID 39301019, 2024). "Transcription factors like NF-κB and STAT3, inflammatory enzymes such as COX-2 and MMP-9, and pro-inflammatory cytokines like IL-1, IL-6, IL-8, and TNF-α are crucial in inflammation-induced cancer." (PMID 39061221, 2024). "Chronic inflammation is one of the major predisposing factors in cancer progression and is indicated by increased plasma levels of C-reactive protein (CRP), interleukin 6, and tumor necrosis factor-alpha." (PMID 38509114, 2024). "VCAM‐1 expression was previously shown to be upregulated on mesothelial cells by TNF treatment, thereby enabling cancer‐mesothelial cell interactions leading to OC cell attachment and invasion." (PMID 38566518, 2024). "MyoD, a muscle-regulatory factor, is likewise restricted at the transcriptional level by NF-κB in cancer cachexia after TNF-α activation." (PMID 39404384, 2024). "In combination with IL6high iCAF and CXCL12high, it was involved in cancer immune reactions through the TNF, NF-kappa B and IL-17 pathways." (PMID 38892065, 2024). "All the studied genes involved in inflammation (MMP9, PTGS2, TNF-α, and IL-6R) were expressed by cancer cells." (PMID 39072314, 2024). "Successful cancer immunotherapy not only needs good cooperation of all kinds of immune cells but also needs cancers sensitive to killing molecules (such as proforin, granzyme, TNF-α, INF-γ) released by T cells and NK cells." (PMID 38740747, 2024). "Regarding cancer treatment, two key effects of TNF blockers on the immune system in patients with inflammatory diseases are noteworthy: they modulate TReg cell activity and reduce T-helper cell inflammatory responses by decreasing IL-17 production." (PMID 39830670, 2024). "In the context of cancer, TNFα plays roles in nearly every stage, including tumorigenesis, tumor growth, angiogenesis, and metastasis but also has anti-oncogenic effects and can be used as an anticancer treatment." (PMID 38443597, 2024). "To understand how the expression of m6A regulators is affected upon initiation of apoptosis in cancer cells, we analyzed RNA-seq data to examine the expression of m6A regulators in HeLa cells treated with cisplatin, doxorubicin, TNF-α, and FAS ligands." (PMID 38665783, 2024). "‘Tumor necrosis factor (TNF) signaling pathway’ is involved in various metabolisms as inflammation, and contributes to cancer progression and metastasis." (PMID 38706317, 2024).
cancer (continued). "The relevance of TNF-α is reflected in calling it a master switch, orchestrating a complex two-way relationship between inflammation and cancer." (PMID 39201656, 2024). "A recent study suggested that TNF-α upregulates the level of prion protein (PrP) in cancer cells and promotes cancer cell migration ADDIN EN.CITE." (PMID 38520006, 2024). "TNFα significantly enhances the response to chemotherapy as well as the release of ATP to enhance cancer immunogenicity via the P2RX7 receptor, promoting DC maturation and proinflammatory cytokine production and leading to T-cell-mediated cytotoxicity." (PMID 38195677, 2024). "Via TGF-β signaling, TANs are polarized into the N1 subtype, which inhibits cancer growth by activating CD8+ T cells through releasing TNF-α, CCL-3, CXCL-9, and CXCL-10." (PMID 39195299, 2024). "With TNF-α being a master regulator of inflammation, drugs that target TNF-α can help treat many diseases such as cancer and cardiovascular diseases, where TNF-α plays a critical role." (PMID 38611112, 2024). "TNFR1 stimulation by tumor necrosis factor alpha (TNF-α)–decorated EVs can induce activation of necroptosis and cell death in cancer." (PMID 38660297, 2024). "TNF plays a dual role in oncoimmunology, either acting as an anti-cancer factor, or behaving as an immunosuppressive cytokine." (PMID 39136013, 2024). "More cytokines subsequently increase the toxicity of Vγ9Vδ2 T cells, further promoting the synthesis and secretion of cytokines such as IFN-γ and TNF-α, thereby inhibiting cancer progression." (PMID 39678510, 2024). "Recently, antibody-TNF-α fusion proteins have been developed to allow local TNF-α effect on cancer cells." (PMID 38789573, 2024). "The comparison of hallmark-signaling pathways in cancer using GSVA scores revealed significant enrichment of immune-related pathways like inflammatory response, TNF-α signaling via NFκB, complement, and interferon α/γ response in the high-infiltration group." (PMID 38311608, 2024). "In module-4 (ME-4), numerous immune-related pathways are significantly enriched, such as PD-L1 expression and PD-1 checkpoint pathway in cancer (ko05235), TNF signaling pathway (ko04668), antigen processing and presentation (ko04612)." (PMID 39724112, 2024). "For example, neutralizing harmful TNF signaling with an anti-TNF-α antibody can inhibit cancer metastasis and invasion." (PMID 38341580, 2024). "The inflammatory cytokine TNF-α is recognized for its dual role in cancer, which depends on factors such as its concentration, duration of exposure, and the presence of other chemokines or cytokines within the TME." (PMID 38254110, 2024). "These upregulated genes were involved in multiple kinase-driven signaling pathways, including many involved in cancer biology, such as TNF signaling, cell–cell and cell–matrix interactions, and DNA damage response pathways." (PMID 38577247, 2024). "The KEGG pathway enrichment analysis showed that DSS treatment KOA was primarily involved in Pathways in cancer, TNF signaling pathway, Toll-like receptor signaling pathway, Apoptosis, and NF-kappa B signaling pathway." (PMID 38194722, 2024). "TRAF2 is an oncogenic protein involved in resistance to anoikis and TNF-mediated apoptosis in cancer cells via NFκB." (PMID 38184997, 2024). "Cancer cell resistance to TNF-α cytotoxicity is a complex, multifactorial, and often unclear process." (PMID 38698424, 2024). "Processes related to inflammation, such as IL-2/STAT5, TNF-alpha signaling via NF-κB and inflammatory response were significantly higher in NrasG12D/PtenKO cancer cells and bulk tumors compared to their NrasG12V-driven counterparts." (PMID 38519484, 2024).
cancer (continued). "TNF-α plays a critical role in the pathobiology of cancer, as it functions either as a protumor cytokine that favors cell proliferation or as an antitumorigenic component in different types of cancers." (PMID 39726047, 2024). "TNF-α is a member of the TNF/TNFR cytokine superfamily and is also a key mediator implicated in inflammation-related cancers." (PMID 38553639, 2024). "In fact, the literature indicates that greater proliferation and improved survival of cancer cells are strongly correlated with high levels of inflammatory mediators, particularly cytokines like interleukin (IL)-6 and tumor necrosis factor (TNF)." (PMID 39000393, 2024). "Both lidocaine and ropivacaine further inhibit cancer cell migration and invasion by blocking TNF-α-induced Src phosphorylation and reducing ICAM-1 expression, which are essential for cellular adhesion in lung cancer cells." (PMID 39597826, 2024). "Taken together, these results showed that TNFα administration enhances cancer immunogenicity via caspase-dependent PANX1 cleavage that mediates ATP release." (PMID 38195677, 2024). "For instance, human lymphoma is, generally, a TNF-sensitive type of cancer that demonstrates good immunotherapy response." (PMID 38698424, 2024). "There was a significant difference in the presence of cancer depending on the level of TNFα (the Mann–Whitney U test, p < 0.01)." (PMID 38051374, 2024). "The results of the KEGG analysis revealed that these DEGs were enriched in cancer-related pathways, such as the TNF signaling pathway and the NF-κB signaling pathway." (PMID 39578715, 2024). "This means that any cell expressing TNFR1 should respond to Smac mimic/TNF-α therapy because the expression of TNFR1 is very common in all types of cancer cells." (PMID 39301019, 2024). "Notoginseoside R1 exhibits anticancer activity by inhibiting TNF-α and suppressing cancer cell proliferation." (PMID 38257247, 2024). "Three years before, the same team had also evaluated the influence of macrophages on the extravasation of cancer cells throughout the secretion of cytokines such as TNFα." (PMID 38619704, 2024). "Treatment strategies that target downstream signaling components or TGF-β, SMAD2, TNFα, and NFκB receptors are being researched to limit the spread of cancer." (PMID 39156270, 2024). "Cell culture models have shown that dipyridamole increases the sensitivities of cancer cells to interferon, tumor necrosis factor α (TNFα), and cisplatin." (PMID 39456628, 2024). "An experiment conducted to investigate the anti-cancer and immunomodulatory activities of polysaccharides found that polysaccharides potentiated the macrophages release of cell factors, TNF-a, NO, and PGE2." (PMID 38668350, 2024). "Under the effect of cancer cells, microglia reduce the expression of iNOS and tumor necrosis factor (TNF)-α and suppress cytotoxic activity." (PMID 39766062, 2024). "The mouse cachexia model demonstrated high levels of high-mobility group box-1 (HMGB1) and tumor necrosis factor-α (TNFα) in cancer ascites." (PMID 39000167, 2024). "This alteration enhances elevated levels of cytokines such as IL-6 and TNF-α to drive cancer progression." (PMID 39156288, 2024). "Infliximab, which binds to an neutralises TNF-alpha, was found to be tolerable in patients with advanced cancer with some evidence of on-target activity." (PMID 39251829, 2024). "Lenvatinib initiates its activity via the inactivation of the p38 MAPK/NF-κB pathway, resulting in decreased levels of circulating TNF-α and IL-6, reducing cancer cell migration and invasion, and enhancing M1 polarization of TAMs in a mouse HCC model." (PMID 39796695, 2024). "In both HCC and breast cancer, M2b macrophages promote cancer cell migration and metastasis through TNF-α." (PMID 39796695, 2024). "TNF-α activates the signal transducer and activator of transcription 3 and NF-kB, promoting cancer growth." (PMID 39099698, 2024).
cancer (continued). "Biologic therapies, particularly TNF-alpha inhibitors, are often avoided due to concerns about their impact on cancer progression or recurrence." (PMID 39766123, 2024). "Under specific scenarios, such as exposure to TNF-α, certain cancer treatment medications, or elevated levels of GSDME, caspase-3 can initiate GSDME-associated pyroptosis." (PMID 38304430, 2024). "These genes were mostly enriched in biological processes, particularly in the PD‐L1 expression and PD1 checkpoint pathway in cancer, TNF signaling pathway, JAK–STAT signaling pathway, and epidermal growth factor receptor signaling pathway." (PMID 38627900, 2024). "The tumor microenvironment, rich in pro-inflammatory cytokines like TNF-α, regulates cancer cells' bioenergetic capacity, immune evasion, and survival." (PMID 39179991, 2024). "Stress conditions, such as hypoxic environment, inflammatory signals such as TNFα and IL-1β, or chemotherapeutics additionally enhance its production by cancer cells." (PMID 39201656, 2024). "Initially defined as an endotoxin‐induced cytokine, TNF-α has demonstrated potent cancer-eradicating properties." (PMID 38698424, 2024). "Intense research established the role of TNF-α in cancer inflammation-mediated metastasis via increased expression of numerous factors, such as VEGF, FGF, EGFR, TGF-β, IL-8, or adhesion molecules, including the activation of JNK and AP-1 pathways." (PMID 39201656, 2024). "The KEGG pathway analysis of LGI3-regulated and PAC-altered genes also demonstrated that the gene groups were associated with the pathways of hypoxia-inducible factor-1 (HIF-1), TNF, cytokines, infectious diseases, and cancer-related pathways." (PMID 38394487, 2024). "Despite its name, TNF-α is found in diseases such as chronic inflammation, autoimmunity, and cancer, particularly in middle-aged and older individuals." (PMID 39830670, 2024). "The inflammatory cytokine TNF-α promotes cancer cell proliferation, migration, and invasion and is mainly secreted by macrophages." (PMID 38601565, 2024). "Agents like PD-L1, TNF-α sourced from macrophages, certain medications, and cancer treatments can induce breast cancer cell pyroptosis via the caspase-8/GSDMC route." (PMID 38304430, 2024). "Some studies have reported an increased risk of certain cancers such as NHL, HL and NMSC in users of TNF-α inhibitors." (PMID 39046819, 2024). "B7 stands out for its ability to significantly reduce cancer cell proliferation in A431, A549, and H1299 cell lines and lower the levels of inflammatory cytokines IL-6 and TNF-α." (PMID 38562527, 2024). "M-DCsTNF alone do not kill cancer cells and function solely as a tool to recognize and attach to cancers and produce TNFα locally." (PMID 39105847, 2024). "The analysis of KEGG pathways also revealed that the putative antihepatic cancer targets identified (Akt1, EGFR, TNF, and ALB) are involved in multiple pathways associated with cancer development and progression." (PMID 39502516, 2024). "As the expression of insufficient quantity of ABCA1 leads to accumulation of cholesterol in cancer cells, prevent releasing of mitochondrial TNF, and hence accelerates the development of the disease." (PMID 38827789, 2024). "More importantly, previous studies have emphasized the importance of the ratio of TNF+ MCs to VEGFA+ MCs for their cancer type-specific functions, and our data revealed that MC2 MCs and MC4 MCs correspond to these two populations." (PMID 39840068, 2024). "TNF-α, a cytokine known for its proinflammatory properties, is widely regarded as an important component in cancer progression." (PMID 38334644, 2024). "Elevated levels of IL-1β, IL-6, and TNF-α have been demonstrated to facilitate the development of cancer." (PMID 39594117, 2024). "We show here that jacaranone enhances TNFα-induced apoptosis and induce caspase-8 activation in cancer cells." (PMID 39769432, 2024).